NOTCH1 (notch receptor 1)
Diseases named in the same sentence as NOTCH1 in open-access papers (continued):
Sharing a sentence is not in itself a finding about the gene and the disease.
tumor (continued). "Tumor cells drive cancer-associated fibroblasts (CAFs) to alter the ECM via TGF-β, Notch1, and WNT pathways, and crosstalk between these cells and the ECM generates tumor heterogeneity." (PMID 38099951, 2023). "Subsequent and more detailed IHC analysis show that NOTCH1 is distributed in the cytoplasm and nuclei of tumor cells." (PMID 38152619, 2023). "In particular, mutation of the NOTCH1 gene has been shown to play a role in R/M ACC, possibly via induction of neoangiogenesis as the mechanism of tumor growth." (PMID 35205740, 2022). "In vivo, inhibiting NOTCH1 signalling impaired M2 macrophage-mediated PCa tumor growth and lung metastasis." (PMID 36439868, 2022). "Hepatocyte-specific Dll4 knockout abolishes the Notch1 signaling and suppresses the tumor progression." (PMID 35064244, 2022). "We will further collect the ESCC samples to determine the effects of the key genes (especially NOTCH1) on radiosensitivity and tumor immune infiltration and perform in vivo experiments to demonstrate the regulatory mechanisms of NOTCH1 in ESCC." (PMID 36119057, 2022). "Both the RT-PCR and western blot results indicate that HIF1α is oncogenic and upregulated when the Redox and Krebs oncometabolites are also highly expressed in CML; on the other hand, Notch1 behaves like a tumor suppressor in CML cases." (PMID 35847841, 2022). "Notch1 contributes to an immune-suppressive tumor microenvironment by inhibiting the expression of SNAP23 and overexpression of IL-6, IL-8, and CCL5 downstream of the pathway, thus affecting the efficacy of immune-checkpoint inhibitors." (PMID 36119081, 2022). "Elevated JAG1 leads to abnormal up-regulation of its receptor Notch-1 accompanied by inhibition of tumor cell apoptosis, development and metastasis of tumors." (PMID 35642021, 2022). "For instance, in vitro experiments using PC cell lines revealed that NOTCH1 activity was promoting cancer cell migration and invasion as well as augmenting aggressiveness of the tumor." (PMID 36613607, 2022). "Cancer stem cells, which are associated with aggressive tumor growth and progression in HNSCC, showed a significantly higher expression of NOTCH1." (PMID 35205828, 2022). "Deregulation of the Notch signalling is crucial for tumour development and progression; therefore, we investigated what effects each treatment had on Notch1 positivity levels." (PMID 34910361, 2022). "In the central regions, HIF-1α was highly expressed in Dox− tumor lysates, whereas it was weakly decreased in the setting of reduced Notch1." (PMID 36183290, 2022). "This study marks the first time the NOTCH1/NICD expression was compared with the proportion of tumor infiltrating lymphocytes." (PMID 35205828, 2022). "Our findings provide evidence that targeting Cbl-b-Notch1 axis represents a promising novel immunotherapeutic strategy to boost anti-cancer T-cell responses and overcome tumor-induced immunosuppression." (PMID 36090975, 2022). "The NOTCH1 signaling activation status of these four ACC tumor models was confirmed by IHC analysis." (PMID 35931701, 2022). "Overexpressed tRF/miR‐1280 suppressed Notch1 as well as Notch2 receptors and downregulated cell proliferation as well as colony formation to reduce tumour growth and metastasis." (PMID 35957621, 2022). "Our findings differ from previous publications, one of which touted Notch1 as a tumor-promoting gene, whereas the other concluded Notch1 is a tumor-suppressor gene." (PMID 36970723, 2022). "The NOTCH1-mediated modulation of surface receptors regulating the interaction with T cells expectedly has effects on the composition of the tumor microenvironment." (PMID 36266281, 2022).
tumor (continued). "Subsequently, we performed a Western blot analysis using the lysates of untreated or treated doxycycline sh-Notch1 xenograft tumors to investigate in vivo intracellular signaling and the mechanisms of the anti-tumor effect." (PMID 36183290, 2022). "In OSCC, the opposing roles of NOTCH signaling in cancer were observed in which NOTCH receptor family members can be tumor-suppressors (NOTCH1, 2) or oncogene (NOTCH1, 3)." (PMID 35742914, 2022). "During radiotherapy, endothelial NOTCH1 activation protects tumor vessels from radiotherapy-induced damage and regulates endothelial-mesenchymal transition." (PMID 35332121, 2022). "BTBD7 predicts low recurrence and represses tumor progression by inactivating Notch1 signaling in BC." (PMID 35655918, 2022). "By using NP-siDCAMKL-1, the growth of both tumor cells and proto-oncogenes (c-Myc and Notch-1) was reduced." (PMID 35717205, 2022). "Mouse models with NOTCH1 mutants receiving specific monoclonal antibodies targeting NOTCH1 have demonstrated partial responses in ACC tumor size." (PMID 35205740, 2022). "In NSCLC, LBX2-AS1 functions as tumor promoter that positively regulates Notch signal markers, Notch1, p21 and Hes1, expressions." (PMID 36229883, 2022). "The deletion of c-MYC at the CD4+CD8+ stage of T cell development prevents tumour formation induced by NOTCH1." (PMID 35681778, 2022). "Co/Ru-UiO-67 can transform tumor CO2 into CO at both cellular level and living tissues, which consequently interacts with relevant signaling pathways (e.g. Notch-1, MMPs etc.)to adjust tumor microenvironment." (PMID 36424645, 2022). "Among all genes, four of them—NOTCH1, INSM1, YAP1, and NEUROD1—emerge as the most significant, being associated with both shorter disease-free interval and high tumor stage and/or risk of recurrence." (PMID 36121500, 2022). "Notch1 signaling promotes M1 TAM differentiation and inhibits MDSCs indicating that Notch1 signaling in immune cells promotes anti-tumor immunity in cancers." (PMID 35154165, 2022). "Among the downregulated genes were several known to activate proliferation of tumor cells (NOTCH1, HMGA2, PTK2, FOSL1, GREM1 and EGR1)." (PMID 35885035, 2022). "To date, the effects of Notch1 signaling on cell apoptosis and proliferation in different kinds of human neoplasms are variable." (PMID 35982489, 2022). "There is also evidence that inhibition of NOTCH1 combined with antiandrogens, including enzalutamide or abiraterone, can efficiently attenuate tumor growth and prevent metastasis in CRPC." (PMID 35954292, 2022). "NOTCH1 is, e.g., important in the regulation of CD8+ T cells and the differentiation of tumor-associated macrophages (TAM)." (PMID 35205828, 2022). "The Notch 1 mode of action is controversial since initial evidence suggested it as a tumor suppressor." (PMID 36286037, 2022). "Notch1 increases expression of M-CSF and SDF-1, which are important in recruitment and development of TAMs (tumour-associated macrophages)." (PMID 35269752, 2022). "The untreated G55 pre‐clinical mouse model demonstrates an upregulation of Notch1 staining having an average of 41% Notch1 positivity staining within the tumour region." (PMID 34910361, 2022). "Meanwhile, the deletion of c-MYC at the CD4+CD8+ stage of T cell development prevents tumour formation induced by NOTCH1." (PMID 35681778, 2022).
tumor (continued). "This upregulation has been related to the NOTCH1 activation of tumor cells, accordingly to their commitment for transformation." (PMID 35392219, 2022). "Notch 1 has previously been described as an oncogene or a tumor suppressor depending on the tumor type." (PMID 35956111, 2022). "In this manner, elevated γ-secretase activity and MAML2 expression induced higher NOTCH1 signalling in PCa cells, which increased tumor cells proliferation and invasion." (PMID 36439868, 2022). "In the case of W390A MLV, mice 7, 11, and 12 had a dominant clone in the tumor with integrations into the Ppp1r16b, Pim1, and Notch1 oncogenes, respectively." (PMID 35852337, 2022). "As a key receptor in Notch signaling, Notch1 has been comprehensively studied and revealed to possess tumor-promoting functions." (PMID 36818671, 2022). "In summary, our results indicate a tumor suppressor function of HEB/TCF12 in T-ALL to mitigate cell proliferation controlled by NOTCH1 in pre-leukemic stem cells and prevent NOTCH1-driven progression to T-ALL." (PMID 35401501, 2022). "To test differences in the concentration of each biomarker between the tumor tissue and the surrounding area, we plotted the median distribution differences (and their interquartile ranges) of NOTCH1, HES1, and THY1 in those areas in the whole population." (PMID 35172861, 2022). "Among the genes whose expression is downregulated in tumor cells following fb-PMT treatment, are MAPK1, AKT, Hedgehog, NOTCH1, and Wnt, all of which encode products involved in intracellular signaling." (PMID 36879662, 2022). "AEA inhibits tumor growth of cholangiocarcinoma cells via upregulation and activation of Notch1, whereas 2-AG promotes tumor growth through upregulation and activation of Notch2." (PMID 36291926, 2022). "Tumor appearance in sh-Notch1 U251-MG xenografted mice was delayed 10 days compared to the tumors in control mice." (PMID 36183290, 2022). "PX-866 led to significant tumor reduction in two NOTCH1-mutant HNSCC patient-derived xenograft models." (PMID 35887235, 2022). "When exploring the mechanisms related to Notch1-driven TNBC tumor formation, the authors found that genes upregulated in the EMT process were highly expressed, while genes downregulated during EMT showed low levels of expression in Notch1-driven tumors." (PMID 36497409, 2022). "Functional characterization has confirmed structural predictions that most of the NOTCH1 mutations in HNSCC are LOF mutations, supporting a tumor-suppressor function for NOTCH1 in HNSCC." (PMID 35887235, 2022). "In contrast, it has been reported that the conditional knockout of Notch1 in hepatocytes accelerates the progression of HCC via inactivation of retinoblastoma tumor suppressor pathway." (PMID 35064244, 2022). "For example, ATF6 regulates the expression of several pro-oncogenic proteins such as GRP78 and Notch1 and plays important roles in tumor growth and resistance to radiotherapy in GBM." (PMID 35150127, 2022). "These regions contained tumor-related genes, such as Muc16, Pik3, and Bcl2 in amplification regions and Hras, Notch1, Apc2, Ccnd1, Batf2, Dapk3, Smarca4, Traf2, Traf3, Cdk3, and Cdh4 in deletion regions." (PMID 36424557, 2022).
tumor (continued). "An example of replacement therapy is the restoration of miR-34a expression in various types of cancer (e.g., lung, colon, pancreas), which led to inhibition of tumor development and inducing programmed cell death by regulating Notch 1, HMGA2 or Bcl-2." (PMID 35269947, 2022). "Notch1 is not only localized in the membrane and cytoplasm but also in the nucleolus of cancer cells and is involved in tumor-suppressing mechanisms." (PMID 35208583, 2022). "Notch1 plays an antagonist role with HIF1α and acts as a tumor suppressor in CML patients, which needs further elucidation." (PMID 35847841, 2022). "Analysis of three publicly available tumor-associated variant databases (TSGene, COSMIC, and cBioPortal) identified the NOTCH1 A2441 site as a commonly mutated codon in breast as well as many other cancers (salivary, adrenal, T-ALL, etc)." (PMID 35186194, 2022). "Recurrent laryngeal cancer demonstrated a higher tumor mutation burden (TMB), as well as higher LRP1B mutation and NOTCH1 mutation rates." (PMID 35911687, 2022). "By reactivating Notch1 in T-cells we aim to lower the threshold of T-cell activation to make tumor-suppressed T-cells more responsive to tumor antigen recognition when infiltrating the tumor microenvironment." (PMID 36090975, 2022). "We found a positive correlation of VM capacity to tumor size and NOTCH1 expression and nuclear localization with statistical significance, implicating that Notch activity is involved with VM formation." (PMID 36548277, 2022). "Consistently, we observed that reactivation of Notch1 increased/restored effector functions and primed T-cells to attack cancer cells in tumor-derived organoids." (PMID 36090975, 2022). "NICD expression differs from NOTCH1 mRNA levels, potentially explaining the previously suggested bimodal role as an oncogene and tumor suppressor in HNSCC." (PMID 35205828, 2022). "In vessels, PON induces vasculotoxicity by activating Notch1, which can be considered as the ‘on‐target off tumour effect’ of this drug." (PMID 35122387, 2022). "The function of NOTCH1 in tumorigenesis is context-dependent, and it can act as an oncogene or tumor suppressor." (PMID 35565454, 2022). "The real-time PCR results confirmed that hypoxia significantly upregulated Notch1, Hes1, and Hey1 mRNA expression in tumor cells (P < 0.05)." (PMID 35982489, 2022). "In an SCC mouse model, genomic aberrations in NOTCH1 induced by mutagenic agents result in an increased tumor burden." (PMID 35332121, 2022). "Second, NOTCH is mostly regarded as a tumor suppressor in HNSCC, and loss-of-function mutations in NOTCH1 are common events in HNSCC." (PMID 34504787, 2021). "Yet, despite the described role as a differentiation inducer and tumor suppressor, NOTCH1 is overexpressed in CD133+ cells, which can initiate new tumor formation upon mouse xenograft." (PMID 34553848, 2021). "NOTCH1 expression is decreased in BC and its activation in cell lines reduces cellular proliferation, suggesting a tumor-suppressive role, whereas NOTCH2 seems to promote cellular proliferation and metastasis, therefore acting as an oncogene." (PMID 33451055, 2021). "Several researches demonstrated that hsa-miR-139 exhibits tumor-suppressive function by regulating NOTCH-1 in CRC." (PMID 33639954, 2021). "We next used shRNA mediated knockdown of NOTCH1 to investigate the effects on brain and niche colonization as well as tumor cell morphology in vivo." (PMID 33579922, 2021). "Intermittent scheduling results in strong modulation of a Notch gene signature, including down-regulation of Notch1 and its target genes, evidence of anti-tumor activity and low toxicity in phase I clinical trials." (PMID 34572582, 2021).
tumor (continued). "Earlier studies had reported and validated that activation of NOTCH1 signalling is related to enhanced tumour stemness, or formation of overt CSCs, which can be isolated from HNSCC patients." (PMID 34944837, 2021). "Given the fact that NOTCH1 is a master regulator in the terminal differentiation of the squamous epithelium and HER3 was mostly observed in the more differentiated tumor cells, we evaluated the contribution of NOTCH1 to the expression of HER3." (PMID 34465724, 2021). "As if to confirm these assumptions, other studies have shown that increased NOTCH1 signalling and enhanced stemness can render tumour tissues less sensitive to standard chemotherapeutic agents, such as cisplatin, docetaxel, and 5-FU." (PMID 34944837, 2021). "The interaction of Notch1 with NFκB promotes tumor progression in colorectal adenocarcinoma through inhibition of apoptosis via the upregulation of the Bcl-xL." (PMID 33681228, 2021). "Mice with intracranial U251-MG xenografts die earlier when the tumor expresses normal levels of Notch1 than when Notch1 is knocked down." (PMID 34804926, 2021). "Downregulation of NOTCH1 expression led to decreased vascular co-option and a reduction of the perivascular tumor cell population." (PMID 33579922, 2021). "Of note, MFAP5 activated Notch 1 signaling in certain tumors, promoting tumor invasion and migration." (PMID 34865619, 2021). "Low CD34 MVD in Notch 1 hot spots and tumor homogeneity on ADC map, which showed correlation with disease recurrence, were contradictory to results of previous studies." (PMID 34642389, 2021). "Our data suggest that NOTCH1 is an important mediator of the resistance of perivascular tumor cells and the resistance promoting effects of NOTCH1 downregulation can be attributed to the induction of TMs." (PMID 33579922, 2021). "Taken together, the inhibition of NOTCH1 signaling reduced the tumor self-renewal capacity and number of CSCs and also decreased transcription factors of self-renewal and markers related to CSCs." (PMID 33673088, 2021). "Specifically, JAG/NOTCH interaction seems to suppress VEGFR/Sflt-1 and promote endothelial cell interactions, and in fact some experimental agents that suppress JAG-mediated NOTCH1 signaling have shown to inhibit angiogenesis and tumor growth." (PMID 33451055, 2021). "In particular, we focus on the dual role of VAV1 in T cell neoplasms, with an emphasis on tumor cell-driven mechanisms that affect VAV1 control of NOTCH1 signaling." (PMID 34571765, 2021). "The characteristic Reed Sternberg (RS) cells, which represent the HL tumor component, highly express Notch1 and Notch2." (PMID 34422814, 2021). "Tumor-associated genes on Chr9q such as FANCC, NTRK2, SYK, and NOTCH1 were amplified; amplification of BRAF, EZH2, MET, CDK6 and HGF located on Chr7 were also detected." (PMID 34895266, 2021). "In contrast, expressing an activated form of Notch 1, 3, or 4 seems to be sufficient to drive tumour formation." (PMID 34295896, 2021). "MiR-34 induces the autophagy and apoptosis of tumor cells, regulates tumor proliferation, and targets notch-1, thereby inhibiting cell invasion in OC." (PMID 34404407, 2021). "The tumor suppressor NOTCH1 and the DNA strand break repair gene PALB2 were more frequently mutated in early onset tumors." (PMID 35003350, 2021). "Overexpression of Smarcd1 inhibited tumor proliferation, migration and chemoresistance possibly via crosstalk with Notch1 pathway." (PMID 33190170, 2021). "We have recently demonstrated that the tumor regulating function of CAFs are governed by the Notch1 signaling pathway." (PMID 33705467, 2021).